KL (klotho)
Diseases named in the same sentence as KL in open-access papers (continued):
Sharing a sentence is not in itself a finding about the gene and the disease.
hearing loss (6 papers, 2015 to 2025). "Premature age-related hearing loss (ARHL) development in Klotho -/- mice demonstrated a protective role of Klotho protein in preserving auditory function and delaying hearing loss progression." (PMID 40737282, 2025). "A recent population study explored the relationship between serum Klotho and hearing loss, but it had certain limitations." (PMID 39610715, 2024). "Collectively, these mechanisms illustrate how elevated levels of Klotho can confer protective effects against hearing loss." (PMID 39610715, 2024). "Several previous studies have tried to examine the expression of the Klotho protein not only in the stria vascularis but also in the spiral ligament of the inner ear, and its relationship with hearing loss in vivo." (PMID 39610715, 2024). "A recent NHANES study investigated the relationship between serum Klotho and hearing loss using a sample of 1,781 individuals aged 20–69." (PMID 39610715, 2024). "Thus, KL potentially represents a protective or therapeutic target for hippocampal or cognitive dysfunction following noise-induced hearing loss." (PMID 33160313, 2020). "Our previous study demonstrated that high levels of FGF23 are associated with hearing impairment in ESRD patients, independently of Klotho." (PMID 36649363, 2023). "However, subsequent research has shown that normalizing 1,25(OH)2D3 levels could alleviate hearing loss in Klotho-deficient mice, appearing that hearing impairment might be indirectly mediated by high systemic 1,25(OH)2D3 rather than by a direct lack of Klotho expression." (PMID 39610715, 2024).
Hypoglycemia (6 papers, 2010 to 2023). A decreased concentration of glucose in the blood. "Mice deficient in Klotho protein show hypoglycemia and high insulin sensitivity, while moderate insulin and IGF-1 resistance was observed in Klotho overexpression." (PMID 38139126, 2023).
hypophosphatemic rickets (6 papers, 2019 to 2025). Rickets due to low serum phosphate concentrations, the cause of which can be nutritional or genetic. "The genetic evaluation of a patient with hypophosphatemic rickets and increased plasma soluble Klotho, revealed a translocation between chromosome 9 and 13, with a breakpoint in vicinity to Klotho (KL) gene." (PMID 34068220, 2021). "Besides elevated Klotho levels, patients displayed increased enzymatic activity protein and FGF23 concentrations accompanied by clinical and biochemical findings of hypophosphatemic rickets." (PMID 34068220, 2021).
ischemia (6 papers, 2017 to 2025). A hypoperfusion of the BLOOD through an organ or tissue caused by a PATHOLOGIC CONSTRICTION or obstruction of its BLOOD VESSELS, or an absence of BLOOD CIRCULATION. "Thus, this study focused on the peri-infarction period, where Klotho protein was administered shortly before and after global ischemia." (PMID 37985893, 2023).
osteoarthritis (6 papers, 2009 to 2025). A noninflammatory degenerative joint disease occurring chiefly in older persons, characterized by degeneration of the articular cartilage, hypertrophy of bone at the margins and changes in the synovial membrane. "The association between Klotho and osteoarthritis has been already verified in several studies." (PMID 31895692, 2019). "Furthermore, this study tracked the usefulness of the optimized formulae to attenuate mono-iodoacetate (MIA)-induced osteoarthritis in rats via modulating HMGB-1/RAGE/NF-κB pathway, Klotho, and miRNA-499a that are implicated in the pathogenesis of OA." (PMID 38502267, 2024). "The association between the systemic immune-inflammation index (SII) and the serum soluble-Klotho concentration (pg/ml) in osteoarthritis (OA) patients is unknown." (PMID 38713671, 2024).
osteomalacia (6 papers, 2012 to 2021). Disorder caused by an interruption of the mineralization of organic bone matrix leading to bone softening, bone pain, and weakness. "A recent report shows that overexpression of nuclear high molecular weight FGF2 isoform increases FGF23/FGFR/KLOTHO signaling, causing phosphate wasting and osteomalacia." (PMID 22629419, 2012).
Parkinson disease (6 papers, 2015 to 2026). A progressive degenerative disorder of the central nervous system characterized by loss of dopamine producing neurons in the substantia nigra and the presence of Lewy bodies in the substantia nigra and locus coeruleus. "Klotho prevented the degeneration of tyrosine hydroxylase-positive neurons in the substantia nigra pars compacta, which is key in the pathophysiology of Parkinson’s disease." (PMID 37425590, 2023). "We believe that this downstream effect of Klotho provides a mechanism for Klotho’s neuroprotective effect as substantiated with a well-known neurotoxic model for Parkinson Disease." (PMID 26452228, 2015). "We conclude that low-level Cmyc expression is essential for maintaining the health of mature dopaminergic neurons and preventing neurodegeneration, and suggest the c-Myc/Klotho axis as a potential therapeutic target for age-related neurodegenerative diseases, including Parkinson's disease." (PMID 40313104, 2025). "A study conducted in Iran showed findings denoting the neuroprotective role of exogenous Klotho in the rat model of Parkinson’s disease and the protective effect against astrogliosis, programmed cell death, and oxidative insults by different signaling cascades." (PMID 37425590, 2023). "CSF levels of Klotho and FGF-23 were lower in Parkinson’s disease patients than in the control group." (PMID 37425590, 2023).
renal carcinoma (6 papers, 2020 to 2023). A carcinoma arising from the epithelium of the renal parenchyma or the renal pelvis. "More research has revealed a significant reduction in KL mRNA expression levels in human renal cancer cells, particularly in ccRCC tissues compared to adjacent normal kidney tissues." (PMID 37726833, 2023). "For example, klotho inhibits transforming growth factor-β1 signaling and suppresses renal cancer metastasis in mice." (PMID 32614356, 2020). "In a different study relating to renal cancer, Klotho expression was inhibited using shRNA; this resulted in increased PI3K/Akt protein expression." (PMID 32585905, 2020). "Klotho expression has been shown to be significantly down-regulated in malignant tissue compared to adjacent non-malignant tissue using immunohistochemical (IHC) techniques, including colorectal, pancreatic, gastric, oesophageal, breast, hepatocellular, ovarian, and renal cancers." (PMID 32585905, 2020). "Further analysis of KL mRNA expression in HK-2 human renal normal cell line and ACHN renal cancer cell line showed significantly decreased expression in renal cancer cells, and even lower expression levels of KL mRNA were found in ccRCC tissue compared to adjacent normal kidney tissue." (PMID 37726833, 2023). "Klotho, PI3K, and AKT protein expression was evaluated in 125 renal carcinoma specimens, and this revealed a negative correlation between Klotho and PI3K/Akt expression." (PMID 32585905, 2020). "Additionally, relative to early renal cancer tissues, advanced renal carcinoma tissues showed lower expression of Klotho and higher levels of PI3K, indicating a negative correlation." (PMID 32585905, 2020). "In addition, the immunohistochemical protein levels revealed that 8 proteins were significantly downregulated in renal cancer tissues relative to adjacent tissues from the Human Protein Atlas (THPA) database (the protein KL was not included in the THPA database)." (PMID 36846720, 2023).
schizophrenia (6 papers, 2013 to 2025). A major psychotic disorder characterized by abnormalities in the perception or expression of reality. "The levels of plasma klotho were positively associated with cognitive performance in schizophrenia patients." (PMID 32612508, 2020). "Fourth, although an elevated klotho level was found in patients with schizophrenia, the mechanisms underlying klotho elevation and the mechanisms by which klotho modulates cognition in schizophrenia are needed to be addressed." (PMID 32612508, 2020). "More studies are required to perform to elucidate the molecular mechanisms underlying plasma klotho elevation in schizophrenia." (PMID 32612508, 2020). "Collectively, these results indicate that anti-aging protein klotho may be implicated in the pathogenesis of schizophrenia, and increased klotho may act as a compensatory factor for the preservation of cognitive function in schizophrenia." (PMID 32612508, 2020). "However, whether plasma klotho is associated with the neurocognitive functions in schizophrenia patients is still unclear." (PMID 32612508, 2020). "Overall, these dissociable patterns of association across cognitive domains indicate the need to exert caution over accepting any generalised direction of effect of Klotho at gene or protein level on cognition in schizophrenia." (PMID 40083947, 2025). "The relationship between Klotho and cognitive dysfunction in schizophrenia has been scarcely explored, with a few paradoxical findings." (PMID 40083947, 2025). "In a previous study, different from the present results, Klotho was found to be higher in patients with schizophrenia, and it was positively correlated with cognitive functions." (PMID 34763683, 2021). "The evaluation of serum levels of Klotho together with cognitive functions in schizophrenia is a fairly new research pursuit, and as such the present study provided valuable data to the extant literature." (PMID 34763683, 2021). "BDNF, GDNF, NGF and Klotho levels were lower in schizophrenia patients than in healthy controls; and, in schizophrenia, on the 20th day of treatment, there was a statistically significant increase in BDNF compared to the 1st day." (PMID 34763683, 2021). "Klotho is a biomarker that has recently been studied in psychiatric disorders, but there is a limited number of studies measuring these serum levels in schizophrenia patients." (PMID 34763683, 2021). "In the present study, Klotho levels were found to be statistically significantly lower in patients with schizophrenia than in healthy controls, with a statistically insignificant increase on the 20th day of treatment." (PMID 34763683, 2021). "In this study, the relationship between cognitive functions and BDNF, GDNF, NGF and Klotho levels in 41 patients diagnosed with schizophrenia who had acute psychotic exacerbation and in 43 healthy controls was examined." (PMID 34763683, 2021). "Klotho, on the other hand, is a relatively new marker, for which few studies in schizophrenia patients have been conducted." (PMID 34763683, 2021). "The levels of plasma klotho were significantly higher in schizophrenia patients than in healthy controls (p < 0.001)." (PMID 32612508, 2020). "We found that patients with schizophrenia had significantly higher levels of plasma klotho than did healthy controls (controls: 844.49 ± 302.94 pg/mL; patients: 1233.25 ± 382.25 pg/mL; t = −5.041, p < 0.001)." (PMID 32612508, 2020). "This study reveals that plasma klotho levels were significantly increased in patients with schizophrenia when compared to gender- and age-matched healthy controls." (PMID 32612508, 2020). "Further studies are needed to investigate the dynamic changes of klotho and the mechanisms by which klotho modulates cognition in schizophrenia." (PMID 32612508, 2020).
schizophrenia (continued). "This study demonstrates that patients with schizophrenia had higher plasma levels of klotho in relation to healthy controls, and plasma klotho was positively correlated with cognitive function in patients with schizophrenia." (PMID 32612508, 2020). "Therefore, new, enhanced studies are needed to clarify the role of Klotho and neurotrophic factors in schizophrenia." (PMID 34763683, 2021). "This study was designed to assess Klotho KL-VS gene effects among schizophrenia patients." (PMID 34226614, 2021). "In this study, the hypothesis that the blood serum levels of BDNF, GDNF, NGF and Klotho in schizophrenia patients and healthy controls would be related to cognitive functions was investigated." (PMID 34763683, 2021). "BDNF, GDNF, NGF and Klotho levels were lower in schizophrenia patients than in healthy controls." (PMID 34763683, 2021). "However, contrary to our expectation, the plasma levels of klotho were found to be increased in schizophrenia patients." (PMID 32612508, 2020). "Additionally, the correlation between plasma klotho levels and cognitive function in schizophrenia patients was examined." (PMID 32612508, 2020). "It should be noted that we had hypothesized that the level of plasma klotho was decreased in patients with schizophrenia because klotho plays a beneficial role in cognition, and cognitions are impaired in schizophrenia." (PMID 32612508, 2020). "However, in other studies, Klotho levels were found to be significantly higher in schizophrenia." (PMID 34763683, 2021). "Intriguingly, elevated plasma klotho was positively correlated with the domains of cognitive tests including attention, working memory, verbal memory, and executive capacity in patients with schizophrenia, which is similar to the relationship observed in healthy individuals." (PMID 32612508, 2020). "Furthermore, hypofunction of NMDARs in the brain of schizophrenia patients might also trigger a compensatory increase of klotho protein." (PMID 32612508, 2020). "Klotho and its relationship with neurotrophic factors and cognition in schizophrenia has not yet been investigated." (PMID 34763683, 2021). "There are a limited number of studies in patients with depression, bipolar mania and schizophrenia, and no enhanced study has been performed to compare the blood serum levels of Klotho and neurotrophic factors with cognitive functions." (PMID 34763683, 2021). "Klotho levels were found to be higher in schizophrenia, but no statistical significance was found." (PMID 34763683, 2021).
thyroid cancer (6 papers, 2020 to 2024). "In a study evaluating the effects of Klotho overexpression in thyroid cancer, attenuation of proliferation and increased apoptotic activity were observed." (PMID 32585905, 2020). "Stanniocalcin (STC), a secreted glycoprotein hormone involved in calcium and phosphate homeostasis that is overexpressed in colorectal, hepatocellular, non-small cell lung cancer, and thyroid cancer, is also regulated by Klotho." (PMID 32585905, 2020). "KL overexpression and sKL induce apoptosis and compromise proliferation of thyroid cancer cell lines FTC133 and FTC238, an effect presumably dependent on stanniocalcin-1." (PMID 33520985, 2020). "Klotho, a newly found anti‐ageing gene, reduces proliferation of thyroid cancer cell lines FTC133 and FTC238 and enhances apoptosis." (PMID 32468698, 2020). "Low differentiation is paralleled by reduced KL expression in human thyroid cancer." (PMID 33520985, 2020). "However, the detailed molecular mechanism of Klotho‐mediated cell proliferation and apoptosis remains unclear, and Klotho‐induced apoptosis was only tested in thyroid cancer cell lines FTC133 and FTC238." (PMID 32468698, 2020).
age (5 papers, 2020 to 2025). A temporal measurement of the time period elapsed since an identifiable point in the life cycle of an organism. "interestingly, mTOR-inhibitors can be considered as up-regulators of klotho, potentially preventing or delaying the onset of age-related cardiovascular dysfunctions, as suggested by our results." (PMID 33758105, 2021). "Since the discovery of Klotho a little over two decades ago, it has become ever more apparent that when Klotho pathways go awry, oxidative stress and mitochondrial dysfunction take over, and age-related chronic disorders are likely to follow." (PMID 32257625, 2020). "The results support the concept that Klotho null mutant mice may be a study model for age-related dry eye disease." (PMID 37887038, 2023). "Taken together, we hypothesize that the protective effect of Klotho on mitochondria attributes to its strong inhibitory effects on Wnt/β‐catenin signaling, as Wnt/β‐catenin signaling activation plays a crucial role in mediating mitochondrial dysfunction and age‐related renal fibrosis." (PMID 33463897, 2021).
endotoxemia (5 papers, 2017 to 2023). "The exacerbated myocardial inflammation and cardiac dysfunction were associated with endotoxemia-caused further reduction of lower myocardial Klotho level in old mice." (PMID 37292905, 2023). "Second, endotoxemia causes a reduction of myocardial Klotho levels in both adult and aging hearts, and the impact of endotoxemia is greater in aging hearts." (PMID 28152512, 2017). "It appears that aging-related relative Klotho deficiency and down-regulation of Klotho by endotoxemia, particularly in aging hearts, plays an important role in the mechanism of the augmented myocardial inflammatory responses and more severe cardiac dysfunction observed in aging endotoxemic mice." (PMID 28152512, 2017). "Interestingly, we observed that endotoxemia caused a further reduction of cardiac Klotho and HSP70 levels." (PMID 28152512, 2017). "Treatment with recombinant Klotho suppresses the inflammatory response and improves cardiac function in aging endotoxemia mice." (PMID 34079811, 2021). "Endotoxemia also caused the depletion of cardiac Klotho and HSP70, but administration of recombinant Klotho preserved the myocardial expression of HSP70 and improved the cardiac function in aging subjects." (PMID 30671457, 2018). "It appears that endotoxemia reduces myocardial levels of Klotho and HSP70, and it has a greater impact on aging hearts." (PMID 28152512, 2017). "When myocardial Klotho levels in aging hearts are down-regulated by endotoxemia, the levels of myocardial HSP70 are also further reduced." (PMID 28152512, 2017). "Klotho levels were lower in aging hearts and were further reduced during endotoxemia." (PMID 28152512, 2017). "Further, it is unclear whether Klotho is expressed in the heart and whether aging and endotoxemia have an impact on myocardial Klotho levels." (PMID 28152512, 2017). "It is possible that Klotho is required to preserve myocardial HSP70 levels, particularly during endotoxemia." (PMID 28152512, 2017). "Interestingly, recombinant IL-37 markedly up-regulated myocardial Klotho levels in old mice with or without endotoxemia." (PMID 37292905, 2023).
peripheral artery disease (5 papers, 2022 to 2024). "Decreased serum klotho levels have also been linked with greater carotid artery intima-media thickness and more advanced peripheral artery disease." (PMID 38610757, 2024). "In adults without known risk factors for cardiovascular disease (CVD), low serum Klotho has been associated with greater carotid artery intima–media thickness and more severe peripheral artery disease." (PMID 36362692, 2022).
pulmonary hypertension (5 papers, 2020 to 2025). Increased pressure within the pulmonary circulation due to lung or heart disorder. "In the monocrotaline induced pulmonary hypertension model in rats, whereas Klotho abrogated the development of pulmonary hypertension in these animals." (PMID 40554265, 2025).
Arrhythmia (4 papers, 2022 to 2025). Any cardiac rhythm other than the normal sinus rhythm. "This may indicate the clinical usefulness of measuring Klotho levels to determine the cut-off value of arrhythmia risk in patients with HF or to assess the inflammatory/oxidative stress response following ICD/CRT-D high voltage intervention." (PMID 41574188, 2025). "Finally, to deeply determine whether the partial lack of klotho is involved in the promotion of pro-arrhythmogenic Ca2+ events, we applied a cellular arrhythmia protocol during electrical stimulation to isolated ventricular cardiomyocytes." (PMID 36674838, 2023).